BRCA1 (BRCA1 DNA repair associated)
Diseases named in the same sentence as BRCA1 in open-access papers (continued):
Sharing a sentence is not in itself a finding about the gene and the disease.
breast cancer (continued). "Perhaps it is because high-risk women without an identified mutation are, on average, at lower lifetime risk for breast cancer (30–40%) than BRCA1 and BRCA2 mutation carriers (60–80%) and thus the balance of risks and benefits is assessed differently." (PMID 19409108, 2009). "About 5%–10% of breast cancer and ovarian cancer are hereditary and 30%–50% of these are due to the autosomal dominant mutations in the susceptibility genes, BRCA1 and BRCA2." (PMID 19594871, 2009). "We have found 13q34 amplification in 4.5% of breast cancer samples, but the frequency increased to 8.1% in BRCA1-associated tumors and to 20% in basal-like tumors." (PMID 19995430, 2009). "On the basis of this finding, we aimed to assess ERCC4-rs744154 as a breast cancer risk modifier in BRCA1 and BRCA2 mutation carriers." (PMID 19920816, 2009). "For example, it is clear from studies on the hereditary forms of breast cancer that mutations in the BRCA1 and BRCA2 genes are often specific to individual populations." (PMID 19956539, 2009). "The number of mutation carriers who developed breast cancer in this study were very small (8 BRCA1 and 11 BRCA2), so the confidence intervals are wide and the results difficult to interpret." (PMID 19409108, 2009). "Gene expression analysis demonstrated that EZH2 is overexpressed in BRCA1-deficient mouse mammary tumors." (PMID 19709408, 2009). "This is in accordance with 90% positivity in a small series of 30 patients with BRCA1 mutation and our previous findings where basal-like breast cancers have an enhanced hypoxic drive and aggressive behaviour." (PMID 19724277, 2009). "In this context of breast cancer, single nucleotide polymorphism (SNP) sensitivity in the BRCA1 gene is of utmost importance." (PMID 22346717, 2009). "This study investigated 3226 gene expression profiles to identify the gene set that can discriminate three types of breast cancer: the BRCA1-mutation, BRCA2-mutation, and sporadic cases." (PMID 19187562, 2009). "This study confirmed the utmost role of BRCA1 5382insC mutation in cancer morbidity: indeed, this single genetic defect is responsible for as many as 1 out of 9 ovarian cancers and 1 out of 25 breast cancers occurring in Russia." (PMID 19338682, 2009). "In most Western populations, 5–10% of all breast cancer cases can be attributed to major genetic factors such as predisposing mutations in BRCA1 and BRCA2, with early-onset cases generally considered as an indicator of genetic susceptibility." (PMID 19491894, 2009). "BSO, a strategy embraced by many of the clinicians in the study, reduces incidence of BRCA1-associated breast cancer also presumably by a hormonal mechanism." (PMID 19409108, 2009). "The mean breast cancer risk for BRCA1 and BRCA2 mutation carriers was 57% (95% CI, 47% - 66%) and 49% (95% CI, 40% - 57%) respectively." (PMID 19825178, 2009). "The two major contributors to hereditary breast cancer are the cancer susceptibility genes BRCA1 and BRCA2." (PMID 19298662, 2009). "Cumulative breast cancer risks by age 70 are estimated to be 65% for BRCA1 and 45% for BRCA2 mutation carriers." (PMID 19619314, 2009). "BLC are a distinct breast carcinomas subtype, accounting for the majority (∼70%) of BRCA1-associated cancers and ∼15% of sporadic ones." (PMID 19440381, 2009). "The cumulative risk of breast carcinoma in carriers of BRCA1/BRCA2 mutations ranges from 45–84% by 70 years of age." (PMID 19724277, 2009). "Extensive breast density is therefore one of the strongest known risk factors for developing breast cancer, second only to age and carrying a BRCA1 or BRCA2 mutation." (PMID 18781174, 2008). "Breast cancer patients with a known deleterious mutation in BRCA1/BRCA2 are more likely to have a family history of breast cancer or ovarian cancer and an earlier age of diagnosis than noncarrier patients." (PMID 18284688, 2008).
breast cancer (continued). "The multiple risks and uncertainty of the risks, e.g. because of the incomplete penetrance of BRCA1/2 mutations, introduces complexity into risk communication regarding hereditary and familial breast cancer." (PMID 18834503, 2008). "Given that only 2% to 3% of breast cancer patients have deleterious mutations in BRCA1 or BRCA2, understanding the clinical significance of this relatively large number of UVs is of great importance." (PMID 18284688, 2008). "The role of tamoxifen in preventing the development of contralateral breast cancer in BRCA1 mutation carriers is not fully understood since it significantly reduces that risk despite low expression of ER." (PMID 18405391, 2008). "Among female BRCA1 mutation carriers, the lifetime risk of breast cancer has been estimated at between 65 and 85%, and the risk of ovarian cancer between 39 and 63%." (PMID 18489799, 2008). "DNA microarray analyses have revealed that this cluster is phenotypically most like the basal-like breast cancer that is caused by deficiencies in the BRCA1 pathways." (PMID 19007432, 2008). "In general, the BRCA1 UV carriers classified as high risk were at increased risk of having a family history of breast cancer or ovarian cancer." (PMID 18284688, 2008). "Although there were differences in the ages of diagnosis of breast cancer in homozygous carriers of the 72Pro allele in BRCA1 and BRCA2 mutation positive groups, the mean age of diagnoses were not significantly different." (PMID 18402691, 2008). "The present study was designed in order to determine the contribution of germline mutations of BRCA1 to sporadic breast cancer cases from all four provinces of Pakistan." (PMID 18759965, 2008). "Hereditary breast carcinomas are predominantly a consequence of loss-of-function germline mutations in one of two major breast cancer susceptibility genes, BRCA1 and BRCA2." (PMID 18431501, 2008). "The average cumulative risk of breast cancer in BRCA1 carriers over all possible modifiers was estimated to be 46% by the age of 70 years for women born before 1920, rising to 59% for women born after 1950." (PMID 18349832, 2008). "The complexity between genistein/soy, the genes it activates/inhibits, and breast cancer risk are also illustrated by the fact that genistein activates ER-α, which in turn interacts with BRCA1 and PTEN." (PMID 18392054, 2008). "The breast cancer and ovarian susceptibility gene 1 (BRCA1) has been shown to inhibit ERα signaling by repressing the AF-2 domain of ERα, which is linked to the ligand-binding domain." (PMID 18847501, 2008). "The morphology of breast cancer found in female BRCA1 and BRCA2 germline mutation carriers has been studied extensively." (PMID 18182994, 2008). "The mean age at breast cancer diagnosis in BRCA1 mutation carriers was 42.98 years and 48.71 years for BRCA2 mutation carriers, respectively." (PMID 18783588, 2008). "First, Brca1-deficient mouse mammary tumors contain heterogeneous populations of cells that share cancer stem cell properties." (PMID 18241344, 2008). "Lately, some studies have reported that the phenotypical and molecular features of BRCA1-associated breast cancers are sporadically shared by TN breast cancers." (PMID 18947390, 2008). "BRCA1 (breast cancer 1) is a well characterized gene in breast cancer since mutations in this gene are responsible of at least 40% of inherited breast cancers and more than 80% of inherited ovarian cancers." (PMID 18673534, 2008). "We separately introduced two breast cancer associated BRCT mutations into the yeast BRCA1 expression plasmid." (PMID 18197258, 2008).
breast cancer (continued). "The identification of a BRCA1 or BRCA2 mutation in familial breast cancer kindreds allows genetic testing of at risk relatives." (PMID 18513387, 2008). "In pursuit of breast cancer culprits, we have come a long way since the early 90’s when the first breast cancer susceptibility gene BRCA1 was mapped and cloned." (PMID 21655367, 2008). "In sporadic breast cancers, BRCA1 mutations are rare; however, 30–40% of sporadic cancers show reduced expression of BRCA1." (PMID 18392054, 2008). "The cumulative risk for breast cancer for a woman carrying a BRCA1 or BRCA2 mutation is estimated to be as high as 85% by the age of 70 years and female carriers are also at a substantially increased risk of developing ovarian cancer." (PMID 18783588, 2008). "We identified 19 sequence variants in BRCA1 gene by screening 66 familial and 64 sporadic breast cancer patients, 70 at risk individuals and 40 control subjects." (PMID 18662409, 2008). "Breast cancers associated with BRCA1 mutations often show characteristic histological features including high grade, high mitotic count, solid architecture and prominent lymphocytic infiltrates, all features resembling so-called medullary cancer." (PMID 18269736, 2008). "cDNA studies of breast cancers with underlying BRCA1 gene mutations show that the most common cancer type in this group is basal." (PMID 18405391, 2008). "Women who have inherited mutations in the BRCA1 tumour suppressor gene have an approximately 66% likelihood of developing breast cancer by the age of 70." (PMID 18392054, 2008). "Expression profiles of short-term fibroblasts have previously been reported to separate carriers of a heterozygous mutation in the BRCA1 or BRCA2 genes from sporadic breast-cancer-affected controls." (PMID 18497862, 2008). "Our current study focus on two promising biomarkers, ERCC1 (excision repair cross-complementing group 1) and BRCA1 (breast cancer susceptibility gene 1)." (PMID 18402708, 2008). "Somatic mutations of BRCA1 have been reported in up to 10% of cases of sporadic ovarian cancer, but they are extremely rare in sporadic breast cancer." (PMID 18241344, 2008). "The aim of this study was to assess the frequency of ERα, ERβ, PgR (progesterone receptor) and HER-2 expression in breast cancer patients with mutated BRCA1 gene and in the control group." (PMID 18405391, 2008). "Hereditary mutations in BRCA1 not only increase the risk of breast cancer but also risk for ovarian and prostate cancer." (PMID 18392054, 2008). "The C to T transition in the 3' untranslated region of the prohibitin (PHB) gene alters mRNA function and has recently been shown to be associated with hereditary breast cancer risk in Polish women harbouring BRCA1 mutations." (PMID 18397521, 2008). "Only one of the previous studies on bilateral breast cancer was restricted to non-BRCA1/2 mutation cases." (PMID 18253122, 2008). "We found that CD44+/CD24- Brca1-deficient mouse mammary tumor cells have cancer stem cell characteristics in vitro, and 50 of these cells are sufficient to initiate tumors in mice." (PMID 18241344, 2008). "Basal-like breast cancer was reported to frequently possess BRCA1 germline mutations, and BRCA1 mRNA expression was also shown to be lower in sporadic basal-like breast cancers." (PMID 18950515, 2008). "This breast cancer incidence is 17.8% (13/73) and 15.1% (8/53) in BRCA1 families with a Ring domain missense mutation and 1806C>T, respectively." (PMID 18783588, 2008). "The BRCA2 DDCV carriers were also at a higher risk of having a first-degree family history of breast cancer or ovarian cancer compared with the normal/polymorphic BRCA2 carriers (odds ratio = 3.69) after adjusting for BRCA1 mutation status." (PMID 18284688, 2008). "Only two BRCA1 and BRCA2 mutations have been found in the Icelandic population, BRCA2 999del5 and BRCA1 G5193A, both being founder mutations explaining a large proportion of familial breast cancer in Iceland." (PMID 18637200, 2008).
breast cancer (continued). "Taken together, the data suggests that the presence of two or more breast cancers with at least one case under the age of 50, and ovarian cancer at any age are significant predictors for the presence of a BRCA1 or BRCA2 mutation." (PMID 18627636, 2008). "The BRCA1 G5193A mutation however is very rare, found in less than 2,5% of hereditary breast cancer families and in 0,2% of unselected breast cancer cases." (PMID 18637200, 2008). "BRCA1 mutation is associated with a high incidence of bilateral disease, and confers an 82% risk for developing breast cancer and an 54% risk for developing ovarian cancer by age 80 years." (PMID 18241344, 2008). "The BRCA1 mutation carriers homozygous for the 72Pro allele had the youngest ages of diagnosis of breast cancer." (PMID 18402691, 2008). "It is commonly assumed that 5–10% of all breast cancer cases can be attributed to a genetic predisposition, of which the breast cancer genes BRCA1 and BRCA2 have been identified as most important." (PMID 18834503, 2008). "In 1994, BRCA1 was identified as the first major gene associated with familial breast cancer predisposition." (PMID 18269736, 2008). "Within the BRCA1 mutation-positive group, homozygous 72Pro carriers had the youngest ages of diagnoses of breast cancer than that of the homozygous 72Arg (p = 0.31) and heterozygous (p = 0.36) carriers, although these observations were not significant." (PMID 18402691, 2008). "We examined the expression profiles of original and serially transplanted mammary tumors from Brca1 deficient mice, and tumor derived cell lines to validate their use for preclinical testing and studies of tumor biology." (PMID 18394172, 2008). "The most widely accepted model proposes that familial breast cancer susceptibility is a consequence of a small number of mutations in BRCA1/2 and a much larger variability in ethnic-specific genes of moderate and/or low penetrance." (PMID 18433505, 2008). "Although those tests were not performed on all the controls, this cannot influence the overall findings of the study since in Poland BRCA1 mutations (unselected for age) occur only in about 3% of all breast cancer patients." (PMID 18405391, 2008). "In the present study, 130 breast cancer patients, 70 at risk individuals and 40 control subjects were analysed for BRCA1 mutations." (PMID 18662409, 2008). "A total of 130 patients with (N = 66) and without (N = 64) a family history of breast cancer, 70 unaffected individuals with a family history of breast cancer and 40 control subjects were analysed for BRCA1 mutations." (PMID 18662409, 2008). "BRCA1 is mutated in about 2.5% to 5% of all breast cancers, in 45% of inherited breast cancer families, and in up to 80% of breast/ovarian cancer families." (PMID 18241344, 2008). "We have previously developed a model (BOADICEA) under which susceptibility to breast cancer is explained by mutations in BRCA1 and BRCA2, as well as by the joint multiplicative effects of many genes (polygenic component)." (PMID 18349832, 2008). "Sporadic tumours with BRCA1 promoter methylation have been reported to be ER and PR negative, or to display similar pathological features to those of BRCA1-mutated hereditary breast cancers." (PMID 18269736, 2008). "Here, we report the results of genetic testing for mutations in the BRCA1 or BRCA2 genes in a series of families with breast cancer in the multi-ethnic population (Malay, Chinese and Indian) of Malaysia." (PMID 18627636, 2008). "In the present study of young breast cancer patients, we identified numerous variants in BRCA1/BRCA2 by direct sequencing, including 22 BRCA1 and 30 BRCA2 new variants that have not been reported in the BIC as of April 2007." (PMID 18284688, 2008). "Since then many inactivating mutations in BRCA1 have been identified as breast cancer predisposition alleles." (PMID 18269736, 2008).
breast cancer (continued). "The basal phenotype is more common in breast cancers arising in young women and in BRCA-1-mutated cancers, to which patterns of disease in black women bear many similarities." (PMID 18182985, 2008). "We demonstrate an association of the CD44+/CD24- phenotype to basal-like and BRCA1 hereditary breast cancer." (PMID 18559090, 2008). "In high-risk families, selected in a genetics service setting, women who test positive for the familial BRCA1/BRCA2 mutation are likely to have cumulative breast cancer risks in keeping with the estimates obtained originally from large families." (PMID 18513387, 2008). "Genetic instability associated with BRCA1 deficiency is believed to be responsible for therapeutic failures, but the role of breast cancer stem cells in tumor progression and drug resistance in this disease are not known." (PMID 18394172, 2008). "There is evidence of susceptibility to breast cancers induced by low dose ionising radiation from diagnostic procedures such as chest x-rays in the case of BRCA1/2 mutation carriers." (PMID 18506189, 2008). "The existence of a large number of breast cancer families who lack linkage to either BRCA1 or BRCA2 suggested that other breast cancer susceptibility genes remained undiscovered." (PMID 18706089, 2008). "Mutation detection led to the discovery of 27 deleterious mutations in 28 breast cancer patients (14 in BRCA1 and 13 in BRCA2)." (PMID 18627636, 2008). "Although the repair-related functions of BRCA1 have been extensively characterized, identifying the underlying mechanism responsible for the onset of breast cancer has remained elusive." (PMID 18197258, 2008). "BRCA1 (MIM113705) is a high risk-associated gene responsible for breast cancer of both hereditary and sporadic origin." (PMID 18759965, 2008). "Expansion of Brca1 deficient mammary tumors by transplantation is a useful alternative for generating sufficient material for studying Brca1-associated tumorigenesis." (PMID 18394172, 2008). "For example, the average cumulative breast cancer risk to age 70 years among BRCA1 carriers is 50% for women born in 1920–1929 and 58% among women born after 1950." (PMID 18349832, 2008). "The breast cancer susceptibility gene BRCA1 encodes a phosphoprotein that is involved in the DNA damage response and regulation of cell cycle checkpoints." (PMID 18377656, 2008). "The breast and ovarian cancer susceptibility gene BRCA1 is implicated not only in familial breast cancers but also in sporadic breast cancers." (PMID 18179693, 2008). "In previous studies Brca1 loss was found to give rise to mammary tumors with a primarily basal-like phenotype." (PMID 18394172, 2008). "The causality between the changes in gene expression induced by genistein/soy intake and altered breast cancer risk can be addressed at least partly by using genetically modified mouse models such as Brca1 or Pten knockout mice." (PMID 18392054, 2008). "Basal-like cancer most closely resembles features of hereditary breast cancer associated with BRCA1 mutation." (PMID 19007432, 2008). "Mutations in splicing cis-acting sequences have been associated with the BRCA1 gene in breast cancer and the KIT oncogene in gastrointestinal stromal tumor." (PMID 19014521, 2008). "The 72Pro allele has been found associated with a younger age of diagnosis of breast cancer in BRCA1 mutation carriers." (PMID 18402691, 2008). "Individuals with germline mutations in the BRCA1 gene have an elevated risk of developing breast cancer, and often display characteristic clinicopathological features." (PMID 18269736, 2008).